CRP (C-reactive protein)
Diseases named in the same sentence as CRP in open-access papers (continued):
Sharing a sentence is not in itself a finding about the gene and the disease.
infectious disease (continued). "CRP is an acute phase reactant that is elevated in patients with infectious disease along with IL-6, the main cytokine that induces CRP release." (PMID 24795865, 2014). "CRP levels increase in acute infectious disease and are observed in acute COVID-19 infection." (PMID 40870417, 2025). "CRP, an acute-phase reactant produced by the liver, plays a pivotal role in inflammatory processes and exhibits high sensitivity in the clinical diagnosis of infectious diseases." (PMID 40123673, 2025). "This may be because preterm infants are prone to various infectious diseases, and CRP alone cannot distinguish the source of inflammation." (PMID 41268112, 2025). "A total of 270 patients over the age of 18 met the Tokyo guidelines 2018 diagnostic criteria of AC, 76 patients with other infectious diseases or no PCT or CRP results were excluded, and finally 194 patients were included in this study." (PMID 40989157, 2025). "Although participants denied the presence of other chronic inflammatory or infectious diseases during structured interviews, no confirmatory diagnostic testing (e.g., CRP, imaging, or microbiological assays) was conducted." (PMID 40869077, 2025). "CRP, as the most widely used and sensitive marker for determining the inflammatory condition of patients, was an important reference for the diagnosis and treatment of infectious diseases." (PMID 40642165, 2025). "Additionally, infectious diseases can increase CRP levels, leading to misinterpretation of the results." (PMID 41179899, 2025). "Elevated CRP levels may also be indicative of non-infectious diseases, such as vascular inflammation." (PMID 39981208, 2025). "Hematology and serum biochemistry revealed an increase in CK, AST, ALT, ALP, and CRP; neutrophilic leucocytosis, lymphopenia, monocytosis, and thrombocytopenia (probably due to destruction or consumption); screening for endocrine and infectious diseases was unremarkable; urine analysis was normal." (PMID 39969014, 2025). "Whether it's a cardiologist or an infectious disease expert, they all understand the implications of a high CRP level" (Participant 5)." (PMID 39092396, 2024). "Addressing these limitations through more extensive prospective studies with standardized methodologies and comprehensive data collection protocols will be crucial for advancing our understanding of the utility of arachidonic acid, IL-6, and CRP as biomarkers in infectious diseases." (PMID 39066228, 2024). "This analysis of real-world data evaluating biomarkers' capabilities to predict in-hospital mortality in children with presumed infectious diseases, demonstrated poor discriminatory capabilities in CRP and white blood cell and strong discriminatory capabilities in pH, PT-INR and procalcitonin." (PMID 39015209, 2024). "Therefore, CRP is an important biomarker in the diagnosis and assessment of the severity of infectious diseases." (PMID 38392603, 2024). "Therefore, this study excluded patients with clinically apparent infectious diseases or abnormally elevated hs‐CRP levels (hs‐CRP > 10 mg/L)." (PMID 38895772, 2024). "As a classic inflammatory marker, CRP is widely used in the diagnosis of infectious diseases." (PMID 37730573, 2023). "However, at least in environments with low exposure to infectious diseases, levels of CRP are relatively stable within individuals." (PMID 35035976, 2022). "CRP is a non-specific measure used to distinguish between infectious and non-infectious diseases caused by viruses or bacteria." (PMID 35958594, 2022). "However, elevated levels of C-reactive protein are often observed not only in AAV but also in infectious diseases, malignant diseases, and other immunological disorders." (PMID 35160215, 2022). "In addition to AL, many other infectious diseases (for example: postoperative pneumonia) cause PCT, CRP and WBC to rise." (PMID 35151339, 2022).
infectious disease (continued). "It is conceivable that in rural areas in SSA, the population is more exposed to infectious diseases than their urban peers, which might lead to higher CRP levels." (PMID 34478414, 2022). "CRP is often used in the early diagnosis of infectious diseases." (PMID 35991149, 2022). "CRP was initially used to differentiate infectious diseases (viral versus bacterial etiology of disease), but over time it has been noticed that this protein is useful in estimating the prognosis of inflammatory process (not necessarily infectious diseases), including KD." (PMID 34682194, 2021). "Besides elevated CRP levels in infectious diseases after acute-phase responses, elevated CRP is also found in auto- or alloimmune diseases, e.g., ITP, FNAIT and TRALI." (PMID 33790888, 2021). "However, the diagnostic properties of suPAR compared to C-reactive protein (CRP) and interleukin-6 (IL-6) are weak in infectious diseases." (PMID 34384460, 2021). "Elevated serum CRP levels in infected patients may be potential biomarkers for the diagnosis of infectious diseases." (PMID 33526982, 2021). "However, CRP levels are elevated not only in the case of inflammation but also in patients with an infectious disease." (PMID 32432067, 2020). "Elevations of CRP occur in association with acute and chronic inflammation due to a range of causes, including infectious diseases and non-infectious inflammatory disorders." (PMID 29993361, 2019). "The diagnostic accuracy of this assay also showed sensitivities and specificities of >90% in most infectious diseases and was clearly superior to contemporary assays such as blood neutrophil counts, C-reactive protein, procalcitonin, and expression of CD64 on blood neutrophils." (PMID 29473432, 2018). "Importantly, normal white blood cell count and C-reactive protein levels excluded an acute infectious disease at initial diagnosis of HF." (PMID 30400209, 2018). "Serum PCR, CRP and WBC levels are of high diagnostic values to neonatal infectious diseases." (PMID 28083019, 2016). "As a marker of infectious disease, C-reactive protein (CRP) is routinely used in Europe and Japan." (PMID 24795865, 2014). "As far as we know, this is the first report suggesting that CRP might act as a protective factor for renal function in infectious diseases." (PMID 20500875, 2010). "In this study, the mean value of serum CRP was 7.36 mg/L; the serum level was raised in 85 patients (30.6%); the increase was mostly moderate; and a high increase of more than 50 mg/L, seen in infectious disease, was found in 6 patients." (PMID 20673375, 2010). "CRP is one component of a first line of innate host defense against infectious diseases." (PMID 15588289, 2004). "Although general dietary supplementation appears to have little effect in people with adequate serum vitamin D concentrations, its importance increases in infectious diseases and an inverse relationship between elevated calcifediol and CRP could be demonstrated." (PMID 39962579, 2025). "However, elevated CRP levels might be related to other inflammatory disorders like infectious diseases." (PMID 40630487, 2025). "Consequently, CRP is frequently used for the early diagnosis of infectious diseases." (PMID 38109177, 2023). "Therefore, CRP is often used for the early diagnosis of infectious diseases." (PMID 35991149, 2022). "In addition, other inflammation markers such as CRP are important to diagnose infectious diseases." (PMID 31527646, 2019). "From a HCW perspective, less pronounced fears of undertreating infectious diseases by withholding antibiotics, stricter prescription monitoring, and the promotion of alternatives to antibiotic treatment appeared to reinforce adherence to the CRP POCT in Chiang Rai." (PMID 30736818, 2019). "Moreover, plasma CRP may suffer influence of other variables, such as inflammatory and infectious diseases, collagenosis, cardiovascular events and some medications." (PMID 27956962, 2009).
infectious disease (continued). "Although CRP and ESR are the most commonly used blood markers for the diagnosis of infectious diseases, they also have been demonstrated to predict the failure of two-stage reimplantation." (PMID 41488484, 2025). "In 141 febrile infants aged 28–90 days presenting to an emergency department, the usefulness of some biomarkers of infectious diseases (calprotectin, procalcitonin (PCT), C-reactive protein (CRP), and white blood cells (WBCs)) were evaluated." (PMID 40650251, 2025). "CSF analysis detected mild mononuclear pleocytosis and was further evaluated for infectious diseases, which detected a TBE IgG‐Ab elevation along with IgA and CRP." (PMID 39969014, 2025). "Elevated C reactive protein (CRP) levels indicate inflammation and can be seen in infectious and non-infectious disease exacerbations." (PMID 38792549, 2024). "The pro-inflammatory cytokine IL-6 has potential as a biomarker in infectious disease as it increases earlier than PCT and CRP, potentially allowing for early detection." (PMID 38921759, 2024). "Measurements of the C-reactive protein (CRP) and procalcitonin (PCT) serve as biomarkers in the treatment of infectious disease." (PMID 38921759, 2024). "The WBC count, and CRP, PCT, TNF‐α, and IL‐6 levels are the most common clinical indicators to assess infectious diseases." (PMID 37102655, 2023). "While the routinely available biomarkers C-reactive protein (CRP) and procalcitonin (PCT) can assist clinicians in determining the etiology of an infectious disease, they lack sufficient specificity." (PMID 36737561, 2023). "Within the present study, NT-proBNP levels correlated with inflammatory markers such as CRP and WBC count, and more than half of the patients suffered from concomitant infectious disease." (PMID 37763116, 2023). "Since then, several studies have repeatedly shown that PSP performs superiorly to CRP and at least as well as PCT in identifying patients with infectious diseases." (PMID 37176638, 2023). "Since its first description as a potential infection biomarker in patients after trauma, PSP has repeatedly been shown to perform superiorly to CRP, and at least as well as PCT, in identifying patients with infectious diseases." (PMID 37176638, 2023). "Erythrocyte sedimentation rate and CRP are closely related to the clinical condition of AAV, but they lack specificity, especially in AAV combined with infectious diseases." (PMID 36961149, 2023). "A limitation of this study is that high leukocyte, CRP, GGT, and PCT concentrations can be found in other inflammatory or infectious diseases." (PMID 37363332, 2023). "This suggests that minor CRP elevation because of the permanent higher burden of infectious diseases on the immune system might impact the association between CRP and HTN differently than the chronic inflammatory burden because of conventional cardiovascular risk factors." (PMID 34478414, 2022). "Our literature search in PubMed using “tocilizumab” with special attention to cases of infectious diseases during TCZ therapy and reported CRP levels at the time of diagnosis yielded a total of 28 case reports on this specific issue." (PMID 33804790, 2021). "Procalcitonin (PCT) and C-reactive protein (CRP) play a special role in infectious diseases, the level of PCT and CRP protein in the infected body was significantly increased, and TA-8 significantly inhibited serum PCT levels during the period of MODS." (PMID 32153412, 2020). "For proof of concept, we chose the C-reactive protein (CRP), which is a biomarker commonly used in the diagnosis of acute, infectious diseases." (PMID 31101112, 2019). "Because the patient serum PCT, CRP, and ferritin levels seemed to be markedly higher than that usually found in SLE patients, we suspected the presence of an infectious disease of undetected origin." (PMID 29742693, 2018).
infectious disease (continued). "The performing of a series of basic laboratory examinations (WBC, CRP) and a urine analysis and culture is recommended in cases of ALTE from a suspected infectious disease." (PMID 29233182, 2017). "Initial lab tests in case of an ALTE due to a suspected infectious disease include a whole blood count (WBC), C-reactive protein (CRP) and urine analysis and culture, according to Italian and AAP GL on UTIs." (PMID 29233182, 2017). "Before treatment, the area under ROC of PCT was 0.967, higher than that of CRP (0.916) and WBC (0.805), suggesting PCT was the most valuable in the early diagnosis of neonatal infectious diseases." (PMID 28083019, 2016). "This study provides a scientific guidance for the clinical diagnosis and treatment of pediatric infectious diseases of newborns through investigating the values of serum PCT, CRP and WBC levels in the diagnosis of pediatric infectious diseases." (PMID 28083019, 2016). "Compared to WBC and CRP, PCT is more sensitive index in the diagnosis of neonatal infectious diseases." (PMID 28083019, 2016). "To date, C-reactive protein (CRP) and procalcitonin (PCT) have been used to monitor infectious disease progression in the intensive care unit (ICU)." (PMID 26880104, 2016). "The median values of CRP and PCT were significantly higher in patients with infectious diseases (CRP: P <0.001; PCT: P <0.001)." (PMID 25407928, 2014). "Similarly, for inflammatory indicators such as C-reactive protein (CRP) and procalcitonin (PCT), which have low specificity, caution is needed to determine whether their elevation is caused by CHD-related chronic systemic inflammation or non-infectious inflammation after cardiac surgery." (PMID 41268112, 2025). "The infectious diseases experts emphasize that no therapeutic decision depends on the serum CRP level per se." (PMID 40565868, 2025). "The changes in WBC (p=0.0028), PCT (p=0.0156), CRP (p<0.0001), and NEU% (p<0.0001) were statistically significant, indicating their potential as indicators for monitoring therapeutic response in infectious diseases." (PMID 40264936, 2025). "Second, we only detected CRP/PNI on admission within 48 h but lacked dynamic monitoring for assessing this infectious disease." (PMID 38376000, 2024). "Our research findings are consistent with previous studies that recommend considering elevated white blood cell count (WBC), C-reactive protein (CRP), and erythrocyte sedimentation rate (ESR) as important indicators when confirming the diagnosis of spinal infectious diseases." (PMID 38173524, 2024). "The CRP level in the infectious disease group was even lower than that in the non-infectious inflammatory disease group, which was unexpected." (PMID 38678116, 2024). "In this observational study, the usefulness of biomarkers of infectious diseases (calprotectin, procalcitonin (PCT), C-reactive protein (CRP), and white blood cells (WBCs) were evaluated in 141 febrile infants aged 28–90 days presenting to an emergency department." (PMID 38786153, 2024). "It has also been suggested that sTREM-1 could be a more sensitive and specific biomarker than traditional indicators, namely CRP and PCT levels, in diagnosing infectious diseases and predicting their prognosis." (PMID 38611690, 2024). "CRP appears on the Essential Diagnostics List produced by WHO and those of individual countries and is recognized to be a simple (albeit imperfect) tool to complement clinical assessments to guide antibiotic treatment or conduct triage for infectious diseases." (PMID 36662693, 2023). "CRP, IL-6, and PCT are commonly used for the diagnosis of various infectious diseases." (PMID 32851063, 2020). "CRP is a traditional inflammatory indicator, but it is not specific in distinguishing between infectious and non-infectious diseases." (PMID 32270860, 2020).
infectious disease (continued). "It was given to 40 of the 198 (20.2%) patients who later turned out to have normal CRP values, and were classified to have non-specified presumptive infections (n = 18) or non-communicable diseases (n = 22)." (PMID 31664120, 2019). "When comparing acute phase protein levels previously reported for various infectious diseases, although some proteins, such as SAA and CRP, are generally upregulated in multiple infections, fold changes were found to be quite different depending on the type of infectious agent." (PMID 30485286, 2018). "Moreover, in contrast to CRP, serum levels of TIMP1 in patients with active AAV were significantly higher than those in patients with infectious diseases." (PMID 28962592, 2017). "The research results demonstrated that, the combined detection of serum PCT, CRP and WBC could be taken as a clinical method for identifying neonatal infectious diseases." (PMID 28083019, 2016). "CRP is a biomarker that is elevated in acute and chronic inflammation such as that in infectious disease or non-infectious chronic diseases." (PMID 26635226, 2015). "Communicable disease appears to be a potentially important contributor to the highly prevalent low HDL-C and high CRP reported here as evidenced by the negative association we found between mean CRP and mean HDL-C levels." (PMID 24888391, 2014). "In the best case, they may require a consultation with an infectious diseases clinician, which the patient would not have had if his/her CRP levels were low." (PMID 40565868, 2025). "This study also did not account for the presence of infectious diseases, which may have affected CRP levels." (PMID 40843450, 2025). "Second, the effect of extraintestinal manifestations, perianal abscess or other infectious disease, which may increase inflammatory biomarkers, on the diagnostic ability of LRG and CRP for endoscopic activity could not be sufficiently assessed." (PMID 39823192, 2025). "Our real-world data analysis suggested that CRP and white blood cell may not be reliable indicators for predicting mortality in children with presumed infectious diseases." (PMID 39015209, 2024). "However, it is worth noting that CRP levels are also elevated in infectious diseases and cannot be used to differentiate infectious from noninfectious inflammation." (PMID 36626467, 2022). "Contrarily, there are no reports evaluating the efficacy of CRP + NLR for infectious diseases." (PMID 36503406, 2022). "CRP levels may not accurately reflect the severity of infectious disease in patients who are being treated with TCZ." (PMID 33804790, 2021). "The aim of this study was to evaluate whether routine C-reactive protein (CRP) and additional inflammatory parameters myeloid-related protein 8/14 (MRP8/14 or S100A8/9) and human neutrophil-derived elastase (HNE) could distinguish KD from infectious diseases." (PMID 32775314, 2020). "Furthermore, the CRP level is not generally elevated in immunocompromized hosts compared to healthy adults when they are suffering from infectious diseases." (PMID 31344108, 2019). "Perceived infectious disease risks when refusing patients antibiotics on the basis of a negative CRP POCT could include social pressure and adverse patient outcomes." (PMID 30736818, 2019). "Since fibrinogen is an acute phase reactant protein and CRP was not measured, it cannot be ruled out that the proband at the time of blood withdrawal could have an infectious disease." (PMID 29299315, 2017). "Comparable CRP values during the follow-up between patients with and without iron supplementation (median 0.74 vs 0.60 mg/dL, p = 0.4) argue against a higher prevalence of inflammatory or infectious diseases in patients not receiving iron supplementation." (PMID 25462819, 2014).